ASCL1 (achaete-scute family bHLH transcription factor 1)
Diseases named in the same sentence as ASCL1 in open-access papers (continued):
Sharing a sentence is not in itself a finding about the gene and the disease.
neuroblastoma (continued). "In neuroblastoma, while the ASCL1-high adrenergic-type (NE) cells are committed to the adrenergic lineage, the ASCL1-low mesenchymal-type (non-NE) neuroblastoma cells are also known to resemble neural crest–derived precursor cells." (PMID 37255415, 2023). "In neuroblastoma, ASCL1 appears to be under direct regulation by the LMO1 and MYCN oncogenes, and its overexpression correlates with poorer survival of patients with tumors." (PMID 37958729, 2023). "Surprisingly, ASCL1 deletion had little effect on the transcription of CRC gene transcripts in these neuroblastoma cell lines, but the ability of MYC/MYCN and CRC component proteins, PHOX2B and GATA3, to bind to chromatin was compromised." (PMID 36263020, 2022). "ZFP36L1 is likewise expressed at low levels in other ASCL1-positive neuroendocrine tumors including neuroblastoma, that like SCLC, are dependent on ASCL130, suggesting that low ZFP36L1 expression is a common feature across high-grade neuroendocrine tumors." (PMID 36008402, 2022). "While playing a redundant role in supporting the oncogenic CRC gene expression, ASCL1 instead appears to play a key role in priming neuroblastoma cells for differentiation." (PMID 36263020, 2022). "To determine the extent to which ASCL1 expression contributes to the rapidly proliferating phenotype of neuroblastoma cells, we compared the cell number of parental and ASCL1 KO cell lines, expanding over time." (PMID 36263020, 2022). "Elevated and stable ASCL1 levels in neuroblastoma cell lines are consistent with these tumour cells being trapped in a neuroblastic developmental intermediate state." (PMID 36263020, 2022). "In neuroblastoma, ASCL1 is a member of the core transcriptional regulatory circuit that maintains the adrenergic (ADRN) phenotype, an aggressive subtype of neuroblastoma." (PMID 35366798, 2022). "In neuroblastoma, ASCL1 has been described as part of a core regulatory circuit of developmental regulators whose high expression is maintained by mutual cross-activation of a network of super enhancers and is further augmented by the activity of MYC/MYCN." (PMID 36263020, 2022). "In neuroblastoma cells a second function of endogenous ASCL1 is to keep chromatin around differentiation genes accessible." (PMID 36263020, 2022). "Increasing ASCL1 in neuroblastoma cells both enhances binding at existing ASCL1 sites and also leads to creation of numerous additional, lower affinity binding sites." (PMID 35366798, 2022). "Taken together, our data allows us to propose a model where endogenous ASCL1 plays two roles in neuroblastoma." (PMID 36263020, 2022). "ASCL1 is generally accepted to be a transcriptional activator, and this has been confirmed in neuroblastoma cells by our previous analysis of changes in gene expression in response to ASCL1 overexpression." (PMID 36263020, 2022). "These analyses are consistent with ASCL1 working in part by controlling the activity of other members of the transcriptional core regulatory circuit in neuroblastoma." (PMID 36263020, 2022). "ASCL1 is known to support an adrenergic (ADRN) identity, a subtype of neuroblastoma associated with more neuronal features that is usually morphologically distinct from an alternative mesenchymal (MES) subtype." (PMID 36263020, 2022). "Here, we wanted to understand the effect of ASCL1 KO on neuroblastoma cell proliferation, differentiation and the impact of ASCL1 KO on the expression and function of the CRC transcription factors." (PMID 36263020, 2022). "In summary, we find that ASCL1 is required for rapid neuroblastoma cell proliferation and to maintain the strong neuronal identity of neuroblastoma cells." (PMID 36263020, 2022). "In contrast, further enhancing ASCL1 activity by overexpression and by preventing the cell cycle-mediated phosphorylation of ASCL1 protein results in neuroblastoma cells re-entering a developmental trajectory leading to cell cycle exit and differentiation." (PMID 36263020, 2022).
neuroblastoma (continued). "Our previous studies have shown that overexpression of ASCL1 in the SH-SY5Y neuroblastoma cell line is sufficient to promote expression of differentiation-associated genes." (PMID 36263020, 2022). "Among all the factors taking part in NB tumorigenesis, recent genomic and functional investigations highlighted BARD1, LMO1, and ASCL1 as important actors in neuroblastoma tumorigenesis as well." (PMID 34884690, 2021). "In the same study, it has been shown that ASCL1 is, itself, a part of the core regulatory circuitry under the adrenergic identity and expression of ASCL1 can induce differentiation arrest in neuroblastoma cells." (PMID 33585251, 2020). "Taken together, our study shows that ASCL1 is an integral member of the neuroblastoma CRC, essential for the formation of the feed-forward autoregulatory loop that drives the oncogenic transformation in concert with MYCN." (PMID 31819055, 2019). "Downregulation of ASCL1 protein expression was observed in multiple LMO1-positive neuroblastoma cell lines after LMO1 knockdown." (PMID 31819055, 2019). "Additionally, we use a single neuroblastoma cell line as a model of ASCL1 activity, but this represents a pathological cellular state with many genetic and epigenetic aberrations." (PMID 40452575, 2025). "We performed ASCL1 ChIP-seq in another MYCN-amplified neuroblastoma cell line (IMR-32) and a non MYCN-amplified cell line (SH-SY5Y), showing that ASCL1 binding at loci associated with both proliferative and neuronal genes is a general feature of ASCL1 functionality in neuroblastoma." (PMID 40452575, 2025). "Similarly, in neuroblastoma, ASCL1 acts as a pioneer factor where it then recruits and cooperates with MYCN at genomic loci to drive adrenergic cell fate conversion." (PMID 40498845, 2025). "However, ASCL1 is expressed at readily detectable levels in many rapidly cycling adrenergic-type neuroblastoma cell lines, where it supports their proliferation." (PMID 40452575, 2025). "Additionally, ASCL1 plays a crucial role in neuroblastoma pathogenesis by promoting cell proliferation and differentiation." (PMID 38726001, 2024). "Finally, we investigated the binding profile of ASCL1, a basic helix–loop–helix TF that is expressed in neuroblastoma cells and is required for cell growth and arrest of differentiation." (PMID 37835497, 2023). "In particular, neuroblastoma cells respond to un(der)phosphorylated ASCL1 by down-regulation of a neuroblastic core regulatory circuit of transcription factors accompanied by cell cycle exit and re-engagement of a genome-wide programme of neuronal differentiation." (PMID 35366798, 2022). "Thus ASCL1’s endogenous role in neuroblastoma cells echoes its normal developmental role sitting at the critical nexus balancing proliferation and differentiation in neuroblasts." (PMID 36263020, 2022). "Additional activation by preventing the CDK-dependent phosphorylation of ASCL1 further engages an extensive programme of cell cycle exit and terminal differentiation, indicating that the level of ASCL1 is critical to determining the balance between proliferation and differentiation in neuroblastoma." (PMID 36263020, 2022). "A better understanding of ASCL1’s function in these cells may lead to therapies that activate the latent ability of neuroblastoma cells to undergo differentiation for patient benefit." (PMID 36263020, 2022). "We also looked at the expression of other neuronal genes that have been identified as direct targets of ASCL1 in neuroblastoma cells by ChIP-seq and RNA-seq analysis and that are involved in neuro-transmitter release, neuronal growth and sensory neuron specification." (PMID 35149717, 2022). "ASCL1 is required for neuroblastoma cell growth and arrest of differentiation." (PMID 31819055, 2019). "Lastly, we analyzed genes and pathways controlled by ASCL1 in neuroblastoma cells." (PMID 31819055, 2019).
neuroblastoma (continued). "Importantly, ASCL1 expression was high in primary neuroblastoma cells, consistent with the origin of most neuroblastomas from sympathetic nervous system progenitors." (PMID 31819055, 2019). "ASCL1, which is one of the few down-regulated genes amongst the DEGs, is also involved in neuronal differentiation, with mRNA downregulation also observed with retinoic acid induced differentiation of neuroblastoma cells." (PMID 29505958, 2018). "Notably, Ascl1 is one of the genes consistently derepressed by miR-124 in N2a neuroblastoma cells, and our future studies will determine the functional significance of this effect." (PMID 24878960, 2014). "Interestingly, when compared with neuroblasts, the neuroblastomas have more genes in common with the self-renewing neural stem cells (535 versus 145), among others the neurogenesis genes ASCL1, GSS, STAT3, UTP11L, ENAH, APBB2, CDK5RAP2, and LARGE." (PMID 16989664, 2006). "While there were no obvious morphological changes in these cells, knockout of ASCL1 significantly reduced the growth rate when compared to wild-type cells, indicating that ASCL1 indeed plays a role in promoting cell cycle progression, as has been seen in other neuroblastoma cell lines." (PMID 40452575, 2025). "However, many pro-proliferative and mitotic terms, including DNA replication and sister chromatid separation, were identified in the GO analysis of downregulated genes, suggesting that ASCL1 actively drives cell cycle progression in proliferating neuroblastoma cells." (PMID 40452575, 2025). "Thus, we propose a model where ASCL1, a key developmental regulator of sympathetic neurogenesis, plays a pivotal role in maintaining proliferation while simultaneously priming cells for differentiation in neuroblastoma." (PMID 36263020, 2022). "Here, we overexpressed ASCL1 in the neuronally-permissive context of neuroblastoma (NB) cells where modest endogenous ASCL1 supports the neuroblast programme." (PMID 35366798, 2022). "Thus, the role of endogenous ASCL1 in maintaining the oncogenic phenotype and cellular identity of different neuroblastoma cell lines remains unclear." (PMID 36263020, 2022). "Indeed, in the embryonic cortex in vivo and in neuroblastoma and glioblastoma cells in vitro, Ascl1SA6 is more efficient at turning on neuronal gene expression and less efficient at transactivating the Sox9 glial promoter compared to Ascl1." (PMID 36061596, 2022). "Interestingly, ASCL1 has been previously shown to act as a pioneering factor in fibroblasts and could thus fulfill a similar role in the context of neuroblastoma tumorigenesis." (PMID 34638267, 2021). "Thus, neuroblastoma cells provide a convenient model system to test whether the potentially conflicting functions of ASCL1 in proliferation and differentiation could be explained by differential activities of this transcription factor at different phases of the cell cycle." (PMID 40452575, 2025). "ASCL1 cis-regulatory elements are targeted by MYCN and additional TF members of the adrenergic (ADRN) neuroblastoma core regulatory circuitry (CRC)." (PMID 37835497, 2023). "In our comparison between two neuroblastoma cell lines representatives of ALK-driven and MYCN-amplified disease, there is clearly heterogeneity of response to ASCL1 knockout despite similar initial expression levels." (PMID 36263020, 2022). "It has been suggested that neuroblastoma, a notoriously heterogeneous disease, may arise from progenitors stalled at different points along this developmental pathway, which is consistent with the very heterogeneous expression of ASCL1 seen in different cell lines." (PMID 36263020, 2022). "Reduced binding of these factors is likely to contribute to the reduced proliferation of ASCL1 KO cells, particularly in the case of MYCN/MYC, whose role in driving proliferation in neuroblastoma is very well documented." (PMID 36263020, 2022).
neuroblastoma (continued). "Here, we have investigated the role of ASCL1 in maintaining proliferation and controlling differentiation in both MYCN amplified and Anaplastic Lymphoma Kinase (ALK)-driven neuroblastoma cells." (PMID 36263020, 2022). "Further support for our model comes from genome-wide analyses showing that CDKN1C and ID2 are likely to be direct targets of ASCL1 in GBM and neuroblastoma cells." (PMID 35149717, 2022). "The adrenergic CRC consists of an interdependent autoregulatory network that includes HAND2, ISL1, PHOX2B, GATA3, ASCL1, and TBX2 and is essential to drive the expression of MYCN and to facilitate the growth and survival of MYCN-amplified neuroblastoma cells." (PMID 34669465, 2021). "Gene expression levels for the adrenergic neuroblastoma CRC members—MYCN, HAND2, ISL1, PHOX2B, GATA3, ASCL1, and TBX2—were assayed by quantitative RT-PCR at 1, 3, and 6 days after treatment with 5 μM ATRA." (PMID 34669465, 2021). "ASCL1 and LMO1 directly regulate the expression of CRC genes, indicating that ASCL1 is a member and LMO1 is a coregulator of the ADRN neuroblastoma CRC." (PMID 31819055, 2019). "Regulatory elements controlling ASCL1 expression are bound by LMO1, MYCN and the transcription factors GATA3, HAND2, PHOX2B, TBX2 and ISL1—all members of the adrenergic (ADRN) neuroblastoma core regulatory circuitry (CRC)." (PMID 31819055, 2019). "To verify that ASCL1 is directly regulated by LMO1, we analyzed the genomic loci bound by LMO1 in neuroblastoma cells." (PMID 31819055, 2019). "Taken together, our results indicate that ASCL1 contributes to the CRC with the other members to ensure viability and establish the ADRN neuroblastoma cell state." (PMID 31819055, 2019). "This indicates that ASCL1 is capable of binding to neuronal targets in G1 phase of the cell cycle in neuroblastoma cells but is not supporting their expression under cycling conditions." (PMID 40452575, 2025). "Interestingly, the oncogene MYCN is also part of the CRC, and neuroblastomas with MYCN amplification and high ASCL1 levels exhibit the worst prognosis." (PMID 40527452, 2025). "ASCL1 and other developmental regulators of neurogenesis form an aberrant ‘core regulatory circuit’ (CRC), that promotes oncogenicity of neuroblastoma cells, where mutually regulated high levels of expression of the circuit genes is usually reinforced by elevated MYCN." (PMID 36263020, 2022). "Besides ASCL1, we found that the receptor tyrosine kinase gene RET was positively regulated by LMO1 and MYCN in neuroblastoma cells." (PMID 31819055, 2019). "Consistently, analysis of primary neuroblastoma samples demonstrated that MYCN-amplified cases showed a higher level of ASCL1 expression than nonamplified cases." (PMID 31819055, 2019). "However, the role of ASCL1 expression in neuroblastoma is not clear, especially as its levels vary considerably in different neuroblastoma cell lines." (PMID 36263020, 2022). "To further test the hypothesis that ASCL1 regulates chromatin accessibility of these transcription factors, we utilised publicly available PHOX2B and GATA3 ChIP-seq datasets in parental BE2C and Kelly neuroblastoma cell lines." (PMID 36263020, 2022). "ASCL1 does not appear to be required to maintain ADRN neuroblastoma cell morphology; in both cell lines, ASCL1 KO cells look similar to their parental ASCL1-expressing counterparts, albeit IMR32 KO cells tend to clump together less readily than the parental line." (PMID 36263020, 2022). "The adrenergic identity of the ADRN subtype of neuroblastoma cells is maintained by a transcriptional core regulatory circuit (CRC) of predominantly developmental regulators of neurogenesis including PHOX2B, GATA3 and ASCL1, whose expression is further maintained by high levels of MYC or MYCN." (PMID 36263020, 2022).
neuroblastoma (continued). "In order to gain further insight into the possible early role of Ascl1 and Meis2 in MYCN-driven tumor formation compared to the other core regulatory circuit members, we compared their time-resolved expression during murine TH-MYCN-driven neuroblastoma tumor development." (PMID 34638267, 2021). "To better understand how ASCL1 expression level and phosphorylation status controls chromatin target binding genome-wide, we have used the neuroblastoma cell line SH-SY5Y (termed NB cells below) as a model representing a broadly permissive neurogenic environment." (PMID 35366798, 2022). "A similar relationship may exist in neuroblastoma cells, in which the more neural crest-like mesenchymal cells do not express ASCL1, and ASCL1 expression is specifically upregulated as cells differentiate along the sympathetic lineage and express members of the ADRN CRC." (PMID 31819055, 2019). "Using CRISPR deletion, we generated neuroblastoma cell lines lacking ASCL1 expression, and these grew more slowly than parental cells, indicating that ASCL1 contributes to rapid proliferation of MYCN amplified and non-amplified neuroblastoma cells." (PMID 36263020, 2022). "However, ASCL1 overexpression did not rescue the cell growth inhibition caused by LMO1 knockdown, indicating that the effects of the CRC in maintaining neuroblastoma cell growth and survival depend on high levels of expression of each member of the CRC and the LMO1 CRC coregulator acting in concert." (PMID 31819055, 2019). "In support of these findings, neuroblastoma cell lines displayed high level expression of ASCL1 together with LMO1 by western blot analysis; however, ASCL1 was not expressed by any T-ALL cell lines examined." (PMID 31819055, 2019).